CD44 (CD44 molecule (IN blood group))
Diseases named in the same sentence as CD44 in open-access papers (continued):
Sharing a sentence is not in itself a finding about the gene and the disease.
infection (continued). "After infection, those cells upregulated the expression of CD11a, CD44 and KLRG-1 and downregulated the expression of CD62L when compared to naïve CD8+ T cells." (PMID 32574175, 2020). "CD4 and CD8 T cells were activated in the MLN after infection with M. tuberculosis as measured by the expression of CD44 as compared to uninfected controls." (PMID 33193338, 2020). "Consistent with our previous observations, LEC-educated cells acquired a predominantly effector phenotype (CD44+CD62L−) by d8 post-infection, and most were found within the KLRG1+CD127− subset." (PMID 31988323, 2020). "In this manuscript we show that exposure to TCS resulted in the reduction of total CD4+ and CD8+ T cell responses as well as activated (CD44+) T cells responding to infection at the peak of the T cell response (10 dpi)." (PMID 33373420, 2020). "Infection with P. yoelii caused extramedullary erythropoiesis, reticulocytosis and expansion of CD8+CD44+CD62L- IFN-γ-producing T cells that form immune synapses with iRetics." (PMID 32913355, 2020). "In all organs we analyzed, the ratio of CD44 expression on CD8-positive cells was increased following infection." (PMID 32664476, 2020). "At 3 h post infection (hpi), over 60% of N. cinerea microcolonies co-localised with actin, CD44 or ezrin." (PMID 32208456, 2020). "HA bound to virion-incorporated CD44 interacts with CD44 on the surface of FRCs and thereby promotes virus binding to FRCs (virus capture) and subsequent trans-infection of CD4+ T cells." (PMID 32752131, 2020). "While several NK receptors remain unchanged at day 8 post infection (p.i.), NK cells upregulated CD44, KLRG1 and CD11b suggesting activation state." (PMID 33370392, 2020). "Even with low levels of IL-2, a major cytokine secreted and responsible for activation of T-cytotoxic cells, an increase in effector Tcyt (CD8+ CD44+ CD62L−) cells was observed in the Junbo mouse middle ear due to NTHi infection." (PMID 31548315, 2019). "The Tcyt cell percentage increased from 7.6 to 11.8% at day 4 of NTHi infection, and the majority of these cells were naive Tcyt (CD44− CD62L+) cells." (PMID 31548315, 2019). "This analysis showed infection of C57Bl/Dk mice or VM/Dk mice with the same prion agent strain gave rise to distinct patterns of CD44 expression in the hippocampus." (PMID 31551718, 2019). "The percentage of total CD44+CD8+ T cells expressing more than one cytokine was highest in BCG-infected mice at D21 post-infection, while total and TB10.4-TET+ cells from Mtb-infected mice demonstrated the highest degree of polyfunctionality at D35." (PMID 31825836, 2019). "Previous studies in other systems have also resulted in mixed findings regarding the role of CD44 in inflammation and infection resolution." (PMID 31226944, 2019). "Our analysis showed a similar upregulation of CD44 expression in the brain at the terminal stage of disease after exposure to prions via intraperitoneal injection, IV injection or oral infection." (PMID 31551718, 2019). "After 24 h of NTHi infection, the percentage of Th cells reduced to 0.39% of total live cells and was dominated by effector T-reg (CD44+ CD25+) cells (74.5%)." (PMID 31548315, 2019). "In contrast, IL-2-producing CD44+CD4+ T cells were already detectable on day 3 but were most abundant on day 15 post-infection." (PMID 30677097, 2019). "Results showed that inhibition of miR-21 by LNA-oligonucleotides significantly increases the CD4+CD44+ 2W+ T cell population compared to untreated LdWT2W infection." (PMID 31608064, 2019). "Specifically, at 60 days post infection, we isolated lymphocytes from the lung tissues and sorted effector-memory Maxi T cells based on CD44+ and CD62L- expression." (PMID 29652930, 2018). "We identified CD44 as the host factor that accounts for the observed producer cell dependence of trans-infection." (PMID 29934525, 2018).
infection (continued). "To investigate the effect of CD44 incorporation on virus capture and trans-infection, we co-transfected an expression plasmid for CD44 and pNL4-3 in 293T cells." (PMID 29934525, 2018). "On day 3 post-infection, adoptively transferred CD44+CD4+T-bet+CD62L− cells were detected in the ear while CD44+CD4+T-bet+CD62L+ cells populated draining lymph nodes (dLNs) but not skin." (PMID 29922288, 2018). "Altogether, these results indicate that HA associated with virus particles and CD44 on the FRC surface are engaged in the same mechanism that promotes FRC-mediated virus capture and trans-infection, presumably through interactions with each other." (PMID 29934525, 2018). "Our results showed a decrease in RSV positive cells following treatment with anti-CD44 antibody prior to infection compared to normal rat IgG control." (PMID 29677209, 2018). "Future studies will focus on the mechanism by which NOD1 transactivates MHC class I and II related genes, and the effect of the correlation between NOD1 and CD44 signaling in pathogen infection." (PMID 28592872, 2017). "On day 7 post-infection, donor OT-I cells proliferated, and differentiated into CD44+CD62L- effector T cells to a similar extent in FAP knockout and WT mice." (PMID 28158223, 2017). "CD44 was expressed equally on CD24int and CD24lo cells in controls, while it was significantly upregulated upon infection on the CD24int and CD24hi cells." (PMID 28091621, 2017). "Equivalent percentages of MAT and CTRL OT-I effector T cells (CD44+CD62L−) were detected at the site of the infection (PEC) and spleen." (PMID 28337207, 2017). "CD44+TCRβ+ T cells were found at very low levels in steady-state lung but after infection infiltrated the tissue." (PMID 27300652, 2016). "Infection decreases cholesterol levels, increases membrane fluidity, disrupts lipid rafts, and redistributes CD44, which is the primary mediator of rolling interactions." (PMID 26785849, 2016). "By day 8 post-infection, cells responding to both viruses had similar levels of CD44 and KLRG-1 while maintaining disparate expression of CD25 and PD-1." (PMID 26915099, 2016). "In this approach, we cannot track Mtb-specific CD4 T cells with tetramers due to the extremely low frequency of donor cells, so we assume that the transferred CD4 T cells that have upregulated CD44 are responding to the infection." (PMID 27244558, 2016). "As early as day 4 post infection, donor cells responding to Clone 13 not only rapidly proliferated but also up-regulated markers of activation including CD44, KLRG-1, CD25 and PD1." (PMID 26915099, 2016). "While CD4+ T cells only had a significant increase in the percentage of CD44+ activated TEM cells, CD8+ T cells demonstrated a significant increase in both, CD44+ and CD44- subsets after infection." (PMID 27272720, 2016). "T cell activation in the CNS cannot readily be deduced by their phenotype as the majority of CD4+ and CD8+ T cells express a CD44+CD62LlowCD69+ effector phenotype throughout infection." (PMID 27708643, 2016). "Having established that CD44 is a key mediator of monocyte rolling on endothelium, we sought to determine the effect of infection on CD44 distribution on the cell membrane." (PMID 26785849, 2016). "Several other studies have shown that CD44–HA signaling can be utilized by pathogens for progression of infections and resulting complications." (PMID 25954275, 2015). "The frequency of CD44+ γδ T cells increased in all organs 14 days after infection, suggesting considerable and long lasting activation of γδ T cells in infected animals." (PMID 25658831, 2015). "Adoptive transfer of lower numbers of naive 1807 cells prior to infection increased the number of activated (CD44+), IL‐17 and IFN‐γ producing 1807 CD4+ T cells >20‐fold in mice infected with 2 million spores versus naïve mice." (PMID 26140582, 2015). "In the case of HIV infection, it appears that exogenous and endogenous HA protect host cells from infection in a CD44-dependent manner." (PMID 25954275, 2015).
infection (continued). "The study showed that in CD44 knockout mice, or mice treated with PEP-1, an inhibitor of CD44–HA interaction, there are significantly less proliferating isthmus stem cells than in wild type mice after infection with H. pylori." (PMID 25954275, 2015). "Previously, CD4+ or CD8+ T cells with down-regulated CD62L and up-regulated CD44 expression were reported to accumulate at the site of infection." (PMID 26439698, 2015). "It was detected by 10NOS2−/− in 15.8±3.1% of CD4+CD44+ (p = 0.0041) at 1 month post infection, a response similar to that seen in NOS2−/− FP cells." (PMID 25210773, 2014). "Surprisingly, modest but significantly higher levels of total T cells (TCRβ+) including higher levels of CD4 (CD44+) and CD8 (CD44+) T cells were detected in the lungs on day 3 post-infection." (PMID 24809749, 2014). "Results of ICS indicate a significant increase in IFNγ- and IL-17A-producing Prn-, FHA-, and Ptx-specific CD4+CD44+ T-cells after infection." (PMID 25137043, 2014). "At 8 days post-infection, the expression of CD44 and CD25 by GranzymeB+CD4+ T cells was strongly decreased, whereas IFN-γ production persisted." (PMID 24367519, 2013). "In response to either CR infection or CR infection+vehicle treatment, staining for both CD44 and Dclk1 increased in the colonic crypts." (PMID 24278135, 2013). "In contrast to the naïve T cell pool, MCMV-infection induced a massive (>10-fold) expansion of blood CD44+ CD62L− effector memory (Tem) CD8+ T cells in young mice independent of Tx." (PMID 22916013, 2012). "Each C57BL/6 mouse had between 200 and 250 2W:I-Ab-specific CD4+ T cells before infection, and these cells expressed small amounts of CD44 (CD44Lo) on the surface as expected for naïve cells." (PMID 21966268, 2011). "Normal mammary tissue CD44+/CD24−/low stem cells showed a prominent innate immune response to infection with oncolytic virus: 1.6 and 4.8 fold induction of IFNα at 4 h and 24 h time points and 2.5 fold induction of IFNβ at 4 h respectively were detected." (PMID 21079774, 2010). "We used a panel of surface antigen markers CD5, CD10, CD19, CD23, CD39, CD40 & CD44 and the intracellular marker Ki-67 to correlate B-cell activation with proliferation during the early stages of infection up to 7 days." (PMID 19784370, 2009). "The level of CD44 was detected by 6 hrs post-infection and was maintained throughout our study suggesting an important contribution to the proliferation and transformation process." (PMID 19784370, 2009). "This may facilitate CD44-mediated internalization by target cells, such as fibroblasts, used in this paper as in vitro infection model, or monocytes which are infected in vivo by T. gondii." (PMID 40871094, 2025). "Mice were administered two anti-CD44 monoclonal antibodies on days 0-3 post-infection." (PMID 41279061, 2025). "This suggests that RA could act in an immunomodulatory manner to promote the adhesion and migration of macrophages in early infection phases through the CD44 pathway." (PMID 40370796, 2025). "Neutrophil numbers were affected by anti-CD44 treatment, but other cell types such as inflammatory monocytes and T cells were not significantly different between anti-CD44 and Isotype-treated groups despite these other immune cell types increasing with infection and expressing CD44." (PMID 41279061, 2025). "When its expression within control and infection EVs was measured, CD44 was found to be significantly upregulated at 72 h in infection-derived EVs compared to control-derived EVs (* p = 0.01), which indicates upregulated EV uptake in host cells after CCoV infection." (PMID 36979955, 2023). "While B cells enhance expression of FoxP3 and decrease expression of CD44 and T-bet by CD4+ T cells in the first two weeks after infection, we found expression of CD44, T-bet, and FoxP3 was similar in CD4+ T cells from WT and MD4 mice at one- and two-weeks post-infection." (PMID 37721965, 2023).
infection (continued). "During long-term infection, a population of activated effector CD44+CD62L- CD8+ T cells massively infiltrate the muscle and may continuously control the spread of the parasites." (PMID 35720419, 2022). "The lack of CD44 expression was found to be associated with reduced leukocyte recruitment to the site of bacterial infection, which negatively affected the course of infection." (PMID 35158641, 2022). "Spp1–integrins/Cd44 were present only in the 6-month samples, and Cxcl4–Cxcr3 and Entpd–Adora2a were present only in the 3-month samples, while Cxcl16–Cxcr6 expression gradually decreased between T cells and endothelial cells as infection progressed." (PMID 36569953, 2022). "However, since the presence of “ready-to-act” CD4+CD44+Ly6C+ T-effector cells requires a persistent infection of Leishmania parasites, achieving durable protection through safer vaccination methods makes TRM populations more desirable to target." (PMID 35419001, 2022). "If FRCs do mediate trans-infection in vivo, the interactions between CD44 and HA may serve as a potential target of antiretrovirals." (PMID 34696365, 2021). "While CD44 has identified functions in T cell differentiation and activation, it is also strongly recognized as a promoter of migration of T lymphocytes to the site of infection." (PMID 34898656, 2021). "The CD44-dependent adhesion mechanism is likely to be the most important for mobilizing the effector T cells at sites of infection and inflammation, because the expression of CD44 is upregulated whereas L-selectin (CD62L), the lymphocyte-expressed selectin, is downregulated in these cases." (PMID 33540535, 2021). "Moreover, splenic primary memory OT‐I cells (those maintained after one infection) and tertiary memory OT‐I cells (those maintained after three infections) exhibited similar phenotypes, based upon CD44, CD127, CD69, CD103 and GrB expression." (PMID 34407221, 2021). "Interestingly, when HIV-1 is produced from CD44-expressing cells including PBMCs and hence incorporates CD44, cell-free infection of this HIV-1 is prevented by HA on CD44-expressing target CD4+ T cells at the step of virus attachment." (PMID 34696365, 2021). "Higher expression of CD44 in milk neutrophils isolated from SCM cows may be important for the recruitment of neutrophils to the mammary tissue during the initial stage of infection." (PMID 34235202, 2021). "Furthermore, CD44 is known to mediate important aspects of the infection of macrophages with Staphylococcus aureus." (PMID 32349323, 2020). "Infection of these mixed chimeras with LASV via intranasal (i.n.)inoculation resulted in strong activation of the polyclonal wild-type T-cell repertoire in which roughly 90% of cells in blood expressed CD44 9 days after infection." (PMID 32817220, 2020). "The ESAT-6-specific IL-17-, IFN-γ-, TNF-α-, and IL-2-producing CD4+ T-cell population in the lungs and spleen was considerably larger than that in BCG-immunised and BCG-primed ESAT-6-boosted mice, and Ag-specific CD4+CD44+ T-cells in the lungs were expanded when compared to pre-infection numbers." (PMID 32545304, 2020). "Interestingly, virion-incorporated CD44 promotes trans-infection mediated by secondary lymphoid organ stromal cells, known as fibroblastic reticular cells (FRC)." (PMID 32752131, 2020). "In light of our results, it is tempting to speculate that activation of NF-ĸB by the infection further up-regulates the expression of CD44, thereby inducing the progression of gastric lesions to more severe pathology." (PMID 30884828, 2019). "CD44 positive astrocytes also displayed accumulation of PrPSc, suggesting they may act as reservoirs for prion production within the CNS during infection." (PMID 31551718, 2019). "Furthermore, the abundance of CD44 in any of the tissue derived erythroid cellular compartments was unaffected by infection." (PMID 29703959, 2018).
infection (continued). "Although the overall fractions of CD4+ T cells of both mice groups were similar and significantly reduced by ~35% among spleen lymphocytes at 12 days after infection, T-bet+/CD44+ activated Th1 cells in the spleens of IFNAR KO mice were significantly higher than those of wild type mice." (PMID 30233599, 2018). "Furthermore, a glycosaminoglycan, hyaluronan (HA), bound to CD44 on virus particles was also required for trans-infection." (PMID 29934525, 2018). "Particularly, activated CD62L—CD44+ T cells showed low levels of CD73 during infection." (PMID 29742141, 2018). "However, overexpression of CD44 in these CD44-knocked out cells restored CD44 incorporation into virions as well as lnFRC-mediated virus capture and trans-infection." (PMID 29934525, 2018). "Upon infection, the residual DP thymocytes expressed higher amounts of CD44 and MHC class I, indicating that the surviving population may be phenotypically more mature and/or activated." (PMID 28091621, 2017). "Importantly, upon infection the residual DP cells in the three subsets expressed higher amounts of CD44 and MHC class I compared to the uninfected controls, indicating survival of the more activated and/or mature DP cells." (PMID 28091621, 2017). "Surface expression of both proteins was reduced on CD44+ T cells following infection." (PMID 28877252, 2017). "In addition to the tetraspanins we have found the membrane-associated levels of CD98, CD44, caveolin-1 and δ-catenin to be downmodulated upon HCMV-infection." (PMID 29121670, 2017). "Importantly, upon infection, CD44 and MHC class I expression were upregulated in CD24hi and CD24int cells." (PMID 28091621, 2017). "Of note, the total Plasmodium infection-induced effector CD4 T cell compartment can be distinguished from irrelevant (naïve) CD4 T cells via published surrogate marker approaches that monitor conformational changes in CD11a and upregulation of CD44 on CD4 T cells following infection or vaccination." (PMID 27732671, 2016). "With infection, as lipid rafts and CD44 get more evenly distributed, CD44 also disengages from the lipid rafts as seen from the decrease in the overlap of intensities of CD44 and lipid rafts from the exact spatial location on the membrane." (PMID 26785849, 2016). "Thus PBMC from mice infected with 102 or 106 pfu Smith strain were evaluated 42 weeks after infection for expression of CD44, CD27, CD62L, and KLRG1 on tetramer positive mCMV-specific CD8 T-cells." (PMID 27870919, 2016). "A lower dose of infection with S. pneumoniae may have given a clearer picture of CD44’s role in the inflammatory response to infection by this bacterium." (PMID 25954275, 2015). "In contrast, CD44 was significantly overexpressed in aged mice compared to young, mock-infected mice, and showed dysregulated expression upon 2-20 infection, peaking at 4 dpi instead of 1 dpi; although the difference from young mice was not statistically significant." (PMID 24558422, 2014). "Interestingly, we observed impaired hepatic accumulation of CXCR6-deficient CD8+ T cells at early time points after transfer and infection which mainly affected CD8+ T cells with a highly activated CD44+CD62L−KLRG1+ phenotype." (PMID 24832098, 2014). "Analysis of the frequencies of the CD44+CD62L−Ly6C+, TCM and CD44+CD62L−Ly6C− subsets within the 2W:I-Ab tetramer+ cells over the course of infection revealed that CD44+CD62L−Ly6C+ T cells accounted for 60% of parasite-specific cells throughout the chronic stage of infection (9–37 weeks)." (PMID 25473946, 2014). "In addition, the frequency of activated CD8+ T cells expressing CD44 was maintained at a slightly higher percentage in KO mice than in WT mice after infection." (PMID 23874199, 2013). "The expression of CD44 was unchanged throughout the events of early infection." (PMID 19784370, 2009). "The engagement of CD44 results in activation of Src, which influences infection." (PMID 19381274, 2009).